MMP2 (matrix metallopeptidase 2)
Diseases named in the same sentence as MMP2 in open-access papers (continued):
Sharing a sentence is not in itself a finding about the gene and the disease.
tumor (continued). "The absence of MMP-2 expression in tumor epithelial cells in the study can be potentially explained by the low-grade tumor samples used in the study or lack of stromal support in cell culture." (PMID 24978435, 2014). "MMP-2 and MMP-9 can promote malignant cell progression and may facilitate the tumour growth, invasion and metastasis because of their ability to degrade type IV collagen of ECM and basement membrane." (PMID 24912879, 2014). "Anthocyanins decrease phospho-GSK3-beta and beta-catenin expression in an in vivo tumor xenograft model, increase AMPK activity in this model, and inhibit cell migration and invasion, possibly by inhibiting MMP-2 (in vitro) and the panendothelial marker, CD31 (in vivo)." (PMID 24666969, 2014). "Our present study showed that a majority of primary tumor cells of the genistein/metastasis(-) subgroup was MMP-2-negative." (PMID 24690154, 2014). "The expression of MMP2 and CDH11 in LNCaP-19 and PC-3 in comparison to LNCaP and elevated expression levels of these genes upon OCM stimulation in LNCaP-19, suggests that castration-resistance potentiates the communication between tumor cells and osteoblasts." (PMID 24292404, 2014). "In tumours, hypoxia stimulates accumulation of HIF-1α by inhibiting proteasomal degradation which in turn stimulates angiogenesis by upregulating the expression of MMP-2 and VEGF." (PMID 25296162, 2014). "Moreover, in a mouse liver metastasis model, tumor-derived CCL2 was found to induce α-SMA-positive HSCs to accumulate at tumor sites and to express MMP-2." (PMID 24966464, 2014). "In particular, MMP2 and MMP9 are key mediators of invasion, metastasis and tumor angiogenesis." (PMID 25238232, 2014). "The univariate regression analysis indicated only the presence of MMP-2 expression in normal colorectal cells as a significant prognostic factor for patients’ survival, although not independent on tumor stage." (PMID 24395652, 2014). "Additionally, the MMP-2/TIMP-2 ratio was higher in CRC than in normal tissues and gradually decreased with tumor stage, depth of invasion, and lymph node metastasis." (PMID 24395652, 2014). "The aim of this study was to measure the expression levels of MMP-2 and MMP-9 in the main tumor mass and in tumor cells on the positive margin and to compare these expression levels with Gleason score and tumor size in patients treated by radical prostatectomy." (PMID 25097794, 2014). "Previously, we found that treatment of LM8 cells with genistein inhibited cell proliferation, decreased the expression and secretion of matrix metalloproteinase 2 (MMP-2), which plays a pivotal role in tumor growth, invasion and metastasis, and decreased cell invasive and motile potential." (PMID 24690154, 2014). "However, MMP2 mRNA and protein levels were positively correlated with AFP levels, clinical TNM stage, tumor size and metastasis." (PMID 25013467, 2014). "Regarding the limitations of this study, direct evidence that MDAP3000 was anchored in the cell membrane after MMP-2 activation in tumor tissues was not obtained." (PMID 25010662, 2014). "Although most MMPs in cancer tissue are produced by stromal rather than cancer cells, clinical evidences showed the tumor cell-expressed MMP-2 and MMP-9 are related with HCC progress." (PMID 24996644, 2014). "However, MMP2, MMP9 and MMP14 are the three major MMPs reported to be involved in tumor angiogenesis." (PMID 25071013, 2014). "Among the MMPs, a subset called gelatinases, consisting of MMP-2 (gelatinase A) and MMP-9 (gelatinase B), has gained the most attention in studies on the acquisition of invasive and metastatic tumor properties, as they degrade collagen IV, the major component of the basement membrane." (PMID 24778099, 2014).
tumor (continued). "In pancreatic cancer, the overexpression of miR-143 significantly decreased the protein levels of MMP-2 and MMP-9, lowered the constitutive activities of RhoA, Rac1, and CDC42 GTPases, and also significantly inhibited cell migration and invasion of tumor cells in vivo and in vitro." (PMID 24670365, 2014). "Moreover, after application of MMP-2 inhibitor, the remaining gelatinase activity, corresponding to MMP-9, was highest in cancers with the most advanced degree of tumor infiltration." (PMID 24778099, 2014). "Therefore, this study yielded additional insight into the potential value of the biomarkers investigated here, particularly, the utility of MMP-2 and MMP-9 expression for predicting the invasive behavior of the tumor and justification for therapy." (PMID 25097794, 2014). "In our study, an increase in the expression of both MMP-2 and TIMP-2 from normal oral epithelium to severe dysplasia suggested that the activation of MMP-2 is dependent on TIMP-2 acting as a cofactor, thereby providing a microenvironment that enhances the spread of tumor cells." (PMID 24591757, 2014). "Interestingly, the levels of SRC and PPARB/D expression were highly and significantly correlated in these tumours, as were the expression levels of PPARB/D andTGFB1 and MMP19, respectively, and to a lesser extent, MMP2, VEGFA, VIM and SNAI1." (PMID 24203162, 2014). "MMP-2 and MMP-9 are responsible for extracellular matrix degradation, and for the consequent neo-angiogenesis, vascular invasion and metastatic potential that characterize malignant tumours." (PMID 25432084, 2014). "MMP-2/72 kD type IV collagenase is the most widely distributed member of MMPs, in which along with MMP-9 cleaves the type IV collagen presents in the basement membrane, which is a prerequisite for tumor cell migration." (PMID 24591757, 2014). "In addition, embelin inhibited the expression of markers of angiogenesis (COX-2, VEGF, VEGFR, and IL-8), and metastasis (MMP-2 and MMP-9) in tumor tissues." (PMID 24694877, 2014). "However, there was significant correlation between MMP2 or HIF-1α protein expression and tumor size, metastasis, presence of a capsule and clinical TNM staging of HCC." (PMID 25013467, 2014). "Suppression of MMP-2, MMP-9 and uPA activity and expression could be a valid strategy to prevent tumor metastasis and invasion." (PMID 25222667, 2014). "Tumor invasion can be induced by macrophages through the production of enzymes and inhibitors that regulate the digestion of the ECM, as well as through the production of several MMPs including MMP-1, MMP-2, MMP-7, MMP-9, MMP-12 and MMP-14." (PMID 24578639, 2014). "Basally, PC3 tumor xenografts are strongly positive for MMP-9, MMP-2, and uPA." (PMID 24900952, 2014). "Both the epithelial and the stromal cells being the source of MMP-2 and TIMP-2 in ECM degradation and subsequent cellular motility may facilitate tumor invasion and metastasis." (PMID 24591757, 2014). "Two representative members, MMP-2 and MMP-9, were reported highly expressed in invasive tumours." (PMID 24912879, 2014). "MMP-2, MMP-9 and MT1-MMP mRNA expression increased significantly with the TNM stage of the tumor." (PMID 23281640, 2013). "Among MMPs, MMP-2 and MMP-9 play a critical role in the modification of ECM and tumour invasion." (PMID 23641796, 2013). "On the basis that astrocyte-secreted MMP-2 and MMP-9 partially mediated tumor cell invasion in vitro, we investigated whether astrocyte-secreted MMP-2 and MMP-9 are involved in astrocyte CM-induced brain metastasis." (PMID 24324647, 2013). "It further supports that IL-19 not only directly facilitates cell proliferation, cell migration, and metastasis but it also prompts the expression of IL-1β, IL-6, TGF-β, MMP-2, MMP9, CXCR4, and fibronectin, which supply of a microenvironment for tumor growth and metastasis." (PMID 23710200, 2013). "MMP-2 and MMP-9 mRNA expression increased significantly with the TNM stage of the tumor." (PMID 23281640, 2013).
tumor (continued). "PER1 expression had negative correlation with MMP-2 expression, MI, PI of tumor cells and tumor weight." (PMID 23405233, 2013). "Furthermore, MMP-9 and to a lesser extend MMP-2 sequester VEGF, required for the initiation of tumor angiogenesis." (PMID 23634280, 2013). "To determine whether ISL could inhibit angiogenesis and VEGFR-2 expression in vivo as what we observed in the in vitro experiments, we detected tumor microvessel density (MVD), VEGF, p-VEGFR-2, MMP2 expression and apoptosis by immunohistochemistry method." (PMID 23861918, 2013). "MMP-2, which has active STAT-binding sites with consensus sequences at the promoter region, has been identified as one of the key STAT3-regulated genes promoting tumor invasion and metastasis." (PMID 23326564, 2013). "Further analysis revealed that MMP-2 expression, MI, PI of tumor cells and tumor weight had negative correlation with PER1 expression." (PMID 23405233, 2013). "The protein TIMP-2, initially described as an inhibitor and regulator of the activity of matrix metalloproteinase-2 (MMP-2), has recently been proven to stimulate cell growth and angiogenesis, as well as inhibit apoptosis, hence contributing to tumour aggressiveness." (PMID 23289974, 2013). "Because MMP-2 is overexpressed in tumor tissues, and has a direct implication in metastasis and angiogenesis of cancer cells, we first examined the effects of HAG on MMP-2 expression." (PMID 24130681, 2013). "Both MMP-2 and MMP-9 are involved with the invasive metastatic potential of tumor cells." (PMID 23764122, 2013). "Consistent with the epigenetic regulation of miRNAs we further showed that demethylation agent or HDAC inhibitor inhibited the secretion of MMP-2 and MMP-9 in EC cells, which further proves that epigenetic regulation of miRNAs play a role in the regulation of EMT and tumor metastasis of EC." (PMID 23680357, 2013). "Furthermore, ACE inhibitors downregulate matrix metalloproteinases, MMP-2, and MMP-9 and inhibit tumor metastasis." (PMID 24223058, 2013). "In this study, we demonstrate that ZF21 also regulates invasion of tumor cells, whereas it does not affect the overall production of MMP-2, MMP-9, and MT1-MMP by the cells." (PMID 23382803, 2013). "Here, we propose that the cure rates for this malignancy might be improved by targeting MMP-2-mediated SDF-1/CXCR4 expression and pathway, thereby preventing reconstitution of tumor vasculature following radiation." (PMID 23381805, 2013). "MMP-2 is thought to be important in the dissemination and invasion of cancer cells and through the activation of MMP-9 thought to activate angiogenesis and thus permits tumor growthand the formation of metastasis." (PMID 23766685, 2013). "PER1 expression was the maximum while MMP-2 expression MI, PI of tumor cells and tumor weight were the minimum at 16 HALO; while at 10 HALO PER1 expression was the minimum but MMP-2 expression MI, PI of tumor cells and tumor weight were the maximum." (PMID 23405233, 2013). "We observed a low MMP2/9 activity in the culture supernatant of these tumor cells with gelatin zymographic gel analysis (data not shown)." (PMID 23894455, 2013). "In addition, MMP2 and MMP9 enzymes play an essential role in cell-matrix interaction and tumor invasion and migration." (PMID 23382905, 2013). "Similarly, higher protease activity for MMP-2 and MMP-9 was detected by zymography in tumor tissue compared to normal tissue." (PMID 23874773, 2013). "Using WM239 cells, the requirement for MMP-2 activity during tumor cell extravasation was evaluated using recombinant CBD (collagen binding domain protein) and MMP-2 HxCD (hemopexin C domain protein), which are known to exert stimulatory and inhibitory effects on pro-MMP-2 activation, respectively." (PMID 24194929, 2013). "Overexpression of E-cadherin in highly invasive cells may reduce tumor cell invasiveness by decreasing MMP-9 and MMP-2 expression." (PMID 23870199, 2013).
tumor (continued). "Metalloproteinases are essential for tumor promotion, progression, and invasion and AP-1 and NF-κB play a dominant role in the transcriptional activation of the majority of MMPs including MMP-9 and MMP-2." (PMID 22776414, 2012). "We hypothesize that enhanced levels of both, MMP-2 and MMP-9 accelerate disruption of the basement membrane and degradation of the dermal equivalent, both events that resemble tumor invasion in vivo." (PMID 22792213, 2012). "Based on our preliminary observations regarding MMP-2 processing of LTBP-3, we hypothesize that osteoblast derived MMP-2 is a key mediator of TGFβ activation in the tumor-bone microenvironment." (PMID 22238668, 2012). "Surprisingly, we observed that host MMP-2 did not impair osteoclast behavior but that osteoblast derived MMP-2 was critical for tumor survival in the bone microenvironment via a mechanism involving the activation of latent TGFβ." (PMID 22238668, 2012). "In addition, levels of MMP-2 and MMP-9 expression in xenograft tumor sections confirmed the in vitro data." (PMID 22681957, 2012). "MMP2 and MMP9, otherwise known as gelatinases, are strongly upregulated in cancers of the lung, colon, breast, skin, and prostate, which are correlated with enhanced tumor invasiveness and metastasis." (PMID 23031673, 2012). "We showed by a gelatin zymography assay that the MMP2 activity was down regulated after SOX2 knocked down, suggesting it is one of the mediators for the SOX2 effect on cell invasion/migration, and tumor metastasis." (PMID 22912670, 2012). "The percent of tumor cellspositive for MMP-2 expression was significantly decreased in the INF-αgroup compared with the controls, and the MMP-2 levels in the combined therapygroup were further significantly reduced compared to the IFN-α, control,and IL-24 groups." (PMID 22569271, 2012). "We presumed that the downregulation of MMP-2, MMP-9 and MMP-14 might alleviate the extracellular matrix (ECM) degradation, thus maintaining the vascular basement membrane and normalizing tumor vasculature." (PMID 22496834, 2012). "To further identify whether the downregulation of MMP-2 in endothelial cells is associated with MT1-MMP, which facilitates peri/extracellular pro-MMP-2 activation, we performed triple-fluorescence immunostaining for PECAM-1, MMP-2 and MT1-MMP on tumor tissue." (PMID 22545131, 2012). "MMP-2 remains in an inactive form in tumor cell lines and tumor tissues in the absence of expression of a membrane-type 1-MMP (MT1-MMP), which converts pro-MMP-2 to its activate form." (PMID 21876694, 2012). "MMP2 and MMP9 were abnormal in 18 (9%) and 38 (19%) of the tumours, respectively." (PMID 23304558, 2012). "Because FoxM1 silencing inhibited the expression and activity of MMP-2, MMP-9 and VEGF that are thought to be critically involved in the processes of tumor cell migration, invasion and metastasis, we tested the effect of FoxM1 deletion on cancer cell migration and invasion." (PMID 23006512, 2012). "We also found that apigenin specifically inhibited MMP-9, but not MMP-2 expression in both tumor tissues and cancer cells." (PMID 22837693, 2012). "In HSA/TIMP-2-treated tumor tissues, MMP-2 expression was profoundly decreased without a change in MT1-MMP expression of PECAM-1-positive cells." (PMID 22545131, 2012). "HSP-90 promotes survival of tumor cell, induces their growth and metastasis even when there are no growth factors via continued protein translation and cellular proliferation; Its client proteins include: KIT, AKT, CDK4, telomerase, Bcl-2, MMP2 and others." (PMID 23164412, 2012). "Our study also showed that expression of MMP-2 and MMP-9 are differentiated among tumours." (PMID 23107277, 2012). "Although normal mucosa MMP-2 levels correlated significantly with their corresponding tumour levels, this was not restricted to or within a specific genotype." (PMID 22472880, 2012).
tumor (continued). "In addition, further work on the methylation status of the TGM-2, MMP-2 and CD24 genes in other multi-factorial human non-neoplastic diseases such as diseases involving scarring or aberrant wound healing are warranted." (PMID 21359202, 2011). "Tumor MMP-2 and -9 activities were only 2-3 fold greater than normal tissue (D p < .05); much less than the 50- and 9-fold increases found in the cathepsin K and L zymograms, respectively." (PMID 21756348, 2011). "It seemed likely that the function of LIV-1 was to stimulate the expression of MMP2, MMP9 and HB-EGF proteins, which in turn activated EGFR and downstream ERK signaling, leading to EMT that facilitated local tumor growth and its distant metastases to bone and soft tissues." (PMID 22110740, 2011). "For example, the production of pro-angiogenic factors, including VEGF, and of tumor invasion related enzymes, such as MMP2 and MMP9, was upregulated in vitro by norepinephrine in several human and non-human cancers, through the β-adrenergic-cAMP-PKA pathway in tumor cells." (PMID 21559428, 2011). "In addition to MMP-2, pre-clinical experiments investigating the efficacy of vaccines targeting MMP-1 and -7 for their anti-tumor activity warrant consideration." (PMID 21385454, 2011). "MMPs may be divided into subgroups, one comprised of type IV collagenases (gelatinases) such as MMP-2 and MMP-9, which play major roles in tumor growth, angiogenesis, and metastatic disease." (PMID 21490745, 2011). "MMP-2, MMP-9 and MT1-MMP were expressed at both the mRNA and protein levels in tumor samples." (PMID 21726449, 2011). "MMP-2, like other MMPs, is a zinc-dependent endopeptidase involved in the degradation of the ECM and plays a role in normal tissue remodeling events such as embryonic development, angiogenesis, tumor migration and wound healing." (PMID 21573219, 2011). "Altogether, our results demonstrate that kahweol is a potent anti-angiogenic compound both in vitro and in vivo, targeting some key steps shared with tumor progression, key molecules involved in ECM remodeling (MMP-2 and uPA), and key molecules involved in inflammation (COX-2 and MCP-1)." (PMID 21858104, 2011). "In this current work, we investigated the mechanisms underlying the lack of MMP-2 epitope presentation via the classical endogenous pathway by MMP-2 cDNA construct transfection into COS-7 cells and into tumor cells." (PMID 20689590, 2010). "In murine melanoma cells, for example, knockdown of EMMPRIN did not reduce the tumor cell-mediated induction of MMP-2, -9, and -14 both in vitro and in vivo, but impaired angiogenesis and metastasis formation." (PMID 24281180, 2010). "Combination therapy with SYY plus IFN-α, by regulating the MMP2/TIMP2 ratio and VEGF expression, could be an effective therapeutic strategy to reverse the tumor-enhancing effect derived from hepatectomy." (PMID 20969807, 2010). "The schedule of the concurrent administration group could inhibit the tumor growth better, and it down-regulated MMP-2 expression through TIMP-2 and EMMPRIN, and thus slow down the tumor growth superiorly to another schedule of treatment." (PMID 20681443, 2010). "MMP-2 and MMP-9 expression were correlated with the tumor EI, EP and the maximum diameters." (PMID 23554622, 2010). "One explanation is that these findings could be due to the link that both MMP-2 and MMP-9 have with apoptosis, which is known to commonly occur with Dz13 treatment of tumour cells." (PMID 20334687, 2010). "Study using breast cancer samples demonstrates that the expressions of MMP-1, MMP-2, MMP-3, MMP-9, urokinase-type PA, and tissue-type PA, and inhibitors (TIMP-1 and TIMP-2) were stronger or equivalent in tumor cells than in fibroblasts or inflammatory cells within the tumor section." (PMID 21152266, 2010). "In particular MMP-2, MMP-9, and plasminogen-activator (uPA) are involved in tumor dissemination." (PMID 24281180, 2010).